LGALS3 (galectin 3)
Diseases named in the same sentence as LGALS3 in open-access papers (continued):
Sharing a sentence is not in itself a finding about the gene and the disease.
pulmonary hypertension (28 papers, 2018 to 2026). Increased pressure within the pulmonary circulation due to lung or heart disorder. "Several studies indicate that galectin-3 is directly associated with multiple pulmonary arterial hypertension phenotypes." (PMID 41010963, 2025). "Galectin-3 was reported as a biomarker in pulmonary hypertension and associated right ventricular dysfunction and has been shown to stimulate the proliferation of smooth muscle cells in vitro." (PMID 37726509, 2023). "Besides, in patients with pulmonary arterial hypertension, significant associations were reported between galectin-3 levels and the RV size and function whereas sST2 levels reflected disease severity." (PMID 35042522, 2022). "In rat models of pulmonary hypertension, increased galectin-3 expression has been observed in VSMCs, with galectin-3 inhibitors shown to slow disease progression." (PMID 37240626, 2023). "Another inflammatory molecule, Galectin 3 (Gal-3) has been shown to correlate with RV function in isolated pulmonary hypertension." (PMID 37324632, 2023). "Nevertheless, relatively higher galectin-3 values were found in SSc patients with pulmonary hypertension or higher modified Rodnan skin score." (PMID 35042522, 2022). "On this basis, the authors of Expert consensus statement on the diagnosis and treatment of pediatric pulmonary hypertension emphasize the fact that galectin-3 is a promising biomarker in adult pulmonary arterial hypertension, setting the direction for further research." (PMID 35410028, 2022). "Moreover, the data showed that patients who have LGALS3 rs4652 pulmonary arterial hypertension and myopathy as predictor variables were statistically significant." (PMID 35807161, 2022). "Galectin 3 has been associated with pulmonary hypertension and fibrosis, and Barman and colleagues have used CRISPR‐mediated deletion of Gal3 to examine its role in pulmonary hypertension in rats." (PMID 32742653, 2020). "Noteworthily, there are also several other biomarkers including circulating angiogenic modulatory factors (VEGFR1, CRP, endostatin, or PCEB-ACE) or inflammatory markers (galectin-3, GDF-15) which were related to the pathophysiology of pulmonary hypertension." (PMID 32566097, 2020). "Previous investigations have demonstrated that Galectin-3 could be induced by PDGF in pulmonary arterial smooth muscle cells (PASMCs), and mediates the effect of PDGF on PASMC proliferation and migration in pulmonary arterial hypertension." (PMID 39407295, 2024). "Galectin-3 is a circulating biomarker of fibrosis whose prognostic role in pulmonary arterial hypertension (PAH) has not been fully explored." (PMID 33105539, 2020). "On the other hand, galectin-3 levels showed increase with the course of the disease and were higher in SSc patients with elevated right ventricular systolic pressure than in those without pulmonary hypertension." (PMID 35042522, 2022).
thyroid (28 papers, 2005 to 2026). "Because they were the best two independent and combined markers, we recommend the use of the galectin-3 + HBME-1 panel to enhance the diagnostic accuracy of follicular-patterned thyroid lesions on FNABs." (PMID 19826479, 2009). "Almost 30 years ago, it was demonstrated that the detection of Galectin-3 expression, the cytoplasm of the thyroid cells showed a diagnostic hallmark of thyroid malignancy and was proposed as a presurgical diagnostic marker of TC, suitable to be applied to the cytological material obtained by FNAB." (PMID 39685748, 2024). "The low specificity suggests that an immunopanel including also HBME-1 and Galectin-3 could obtain the highest diagnostic accuracy in thyroid lesions." (PMID 26186733, 2015). "It turns out that galectin-3 remains for now the only one of the AGE receptors thought to be a marker of thyroid diseases." (PMID 33920190, 2021). "An immunohistochemical study suggested a strong correlation between galectin-3 and β-catenin expression in benign and malignant thyroid tissues." (PMID 34035807, 2021). "Immunohistochemical studies on thyroid borderline lesions such as WDT-UMP have always focused on the panel of well recognised markers like galectin-3, HBME-1 and CK19." (PMID 25907675, 2015). "Following investigations clearly show that galectin-3 expression in paraffin-embedded cytological thyroid sediments (cell blocks) obtained by fine-needle aspiration biopsy was significantly higher compared to their histological counterparts." (PMID 23658855, 2010). "They recommended performing galectin-3 IHC staining of thyroid lesions using biotin-free detection system." (PMID 20181018, 2010). "Many studies have evaluated the immunoexpression of a single marker such as galectin-3 or CK19 in the investigation of various thyroid lesions." (PMID 20181018, 2010). "In studies dealing with galectin-3 in thyroid lesions including the largest study of Bartolazzi, positivity for a proportion of benign lesions has always been reported in cytological as well as histological samples." (PMID 16251880, 2005). "Altogether these results show that galectin-3 constitutes a useful marker in the diagnosis of thyroid lesions classified as undeterminate by conventional cytology." (PMID 16251880, 2005). "Galectin 3 (Gal-3), which is highly over-expressed in aggressive PTC but undetectable in normal and benign thyroid conditions, is already clinically adopted as an important diagnostic biomarker to distinguish thyroid malignancy from benign nodules." (PMID 36936158, 2023). "The continuous upregulation of Lgals3 gene expression by neonatal irradiation may also be related to thyroid tumorigenesis." (PMID 34880333, 2021). "In fact, other group confirmed that, in addition to galectin-3, there is no significant adjunct diagnostic value in Gal-7 for thyroid malignancy." (PMID 29951528, 2018). "The aim of this study was to establish whether the methylation state of the galectin-3 gene is a candidate molecular marker for thyroid malignancy." (PMID 23946782, 2013). "Galectin-3 has been also involved in thyroid tumorigenesis through its anti-apoptotic activity." (PMID 19893615, 2009). "Additionally, galectin-3 is highly specific for thyroid malignancy." (PMID 32190664, 2020). "Immunohistochemical profiles were studied by markers previously found to be related to thyroid malignancy such as CK19, galectin-3, HBME-1, and cyclin D1." (PMID 33991306, 2021). "Some promising IHC markers for differential diagnosis of thyroid lesions include CD56, Hector Battifora mesothelial (HBME-1), galectin-3 (Gal-3) and CK19, but a combination of several of these markers must be used together in order to achieve high sensitivity and specificity." (PMID 37444514, 2023).
thyroid (continued). "In the present pilot study we seek to ascertain the efficacy of CD56 in discriminating between benign and malignant thyroid FNAC specimens and its role as an additional marker in the panel made up of HBME-1 and Galectin-3 as previously analyzed in some papers published by our group." (PMID 26186733, 2015). "In this study, our goal was to evaluate the usefulness of using four of the most promising IHC markers (galectin-3, HBME-1, CK19, and Ret oncoprotein) on FNA cell block sections of thyroid lesions to identify the most helpful marker(s) in separating benign from malignant nodules." (PMID 19826479, 2009). "The purpose of LNAB and galectin-3 expression analysis is not to replace conventional thyroid FNA-cytology, which remains in our opinion, the most important screening method for thyroid proliferations." (PMID 16804521, 2006).
thyroid nodule (28 papers, 2005 to 2024). A small circumscribed mass in the THYROID GLAND that can be of neoplastic growth or non-neoplastic abnormality. "Incorporating galectin-3 testing into diagnostic algorithms helps stratify the risk of malignancy in thyroid nodules, aiding doctors in deciding the best course of action, such as surgery or careful observation." (PMID 38501105, 2024). "Our objective was to investigate the role of Galectin-3 in fine needle aspirates of thyroid nodules as a prospective diagnostic marker and consequently its ability to differentiate benign from malignant neoplasms." (PMID 28811803, 2017). "The immunodetection of galectin-3 on LNAB histological specimen from thyroid nodules has shown higher diagnostic accuracy, especially specificity, than FNAB cytology." (PMID 23536779, 2013). "The diagnostic potential of galectin-3 expression analysis in distinguishing benign from malignant thyroid nodules has been recently evaluated in a large International Multicentric Study." (PMID 16804521, 2006). "Association of Galectin-3 expression with benign and malignant Thyroid nodules." (PMID 28811803, 2017). "Recent large prospective studies have emphasized the ability of genetic markers (BRAF, RAS, RET/PTC, and PAX8/PPARγ) and protein markers (galectin-3) to significantly improve and affect the preoperative diagnostic accuracy especially for patients who have indeterminate thyroid nodules." (PMID 23326756, 2012). "Galectin-3 immunohistochemistry has proven to be an effective method for discriminating between benign and malignant thyroid nodules." (PMID 38501105, 2024). "High galectin-3 expression indicates malignancy, which aids in the preoperative evaluation of thyroid nodules." (PMID 38501105, 2024). "Since the introduction of Galectin-3 based ThyroTest in the algorithm of suspicious thyroid nodules, we observed a dramatic reduction in the surgical procedure, manly performed to obtain a diagnostic characterization of the lesions." (PMID 39685748, 2024). "Although Galectin-3 has high sensitivity, it has poor specificity, as it is expressed in most benign thyroid nodules and chronic lymphocytic thyroiditis (CLT)." (PMID 37951919, 2023). "Taken as a whole, it can be deduced that the combined use of galectin-3, HBME-1and CK19 improves the sensitivity and diagnostic accuracy of thyroid nodules." (PMID 34711014, 2021). "For validation, the expression of SLC5A5 and LGALS3 was measured in a larger number of thyroid nodule patients." (PMID 30781659, 2019). "Concluding, galectin-3 immuno-PET targeting represents a new potential diagnostic method for in vivo detection and biological characterization of thyroid nodules, which deserves to be further improved for clinical translation." (PMID 29393868, 2018). "We propose the use of Galectin-3 immunostaining in preoperative FNAC of thyroid nodule more than ever to evaluate the indeterminate cytology and to avoid unnecessary aggressive surgical interference in benign lesions." (PMID 28811803, 2017). "Many series, as well as the present study, have showed that Galectin-3 is useful as a marker of malignancy in thyroid nodules although some studies have produced conflictive results." (PMID 21052476, 2010). "We recommend the use of a small panel of galectin-3 and HBME-1 as an adjunct to standard cytomorphology criteria to enhance the diagnostic accuracy of thyroid nodules with follicular-patterned cytologic features." (PMID 19826479, 2009).
thyroid nodule (continued). "The galectin-3 based radio-immunoscintigraphy proposed here, provides biological information about thyroid nodules and represents an useful guide to correctly identify those thyroid proliferations that should be cytologically evaluated and/or promptly excised." (PMID 19020658, 2008). "In conclusion, LNAB plus galectin-3 expression analysis when applied preoperatively to selected thyroid nodules candidate to surgery can potentially reduce unnecessary thyroid resections." (PMID 16804521, 2006). "In the present study, the potential interest of galectin-3 in the diagnosis of thyroid nodules categorised as undeterminate by cytology was evaluated in a prospective series of fine-needle aspirates." (PMID 16251880, 2005). "In a very recent review on the optimal management of thyroid nodules, galectin-3 was mentioned as an immunohistochemical marker having shown to be potentially interesting in preliminary studies." (PMID 16251880, 2005). "At least 50 molecular markers have been analyzed in patients with thyroid nodules, and the use of immunocytochemistry for detecting abnormally high levels of thyroid peroxidase and galectin-3 in nodule FNAC seems to be particularly promising for predicting malignancy." (PMID 24597765, 2014). "Using a combination of at least two-marker gene sets, a specificity of up to 87% (LGALS3/HGD1) and a sensitivity of up to 82% (LGALS3/TG) emphasises that molecular analysis of FNAB is a promising tool to improve the differential diagnosis of thyroid nodules (Hegedüs, 2010)." (PMID 22223087, 2012). "The use of reverse transcriptase (RT-PCR)–polymerase chain reaction technique for evaluation of galectin-3 expression in thyroid nodules, in fact, can produce false positive results because foamy thyroid macrophages, endothelial cells and some activated lymphocytes normally express galectin-3." (PMID 16804521, 2006). "Several studies have shown that a lower elasticity of the thyroid nodule is correlated with a higher incidence of malignancy, although this could also be due to other histological features, such as the presence of fibrosis and the expression of galectin- 3 and fibronectin-1." (PMID 34129178, 2021). "Among these, Galectin-3 (Gal-3), a β-galactoside-binding protein involved in regulating cell-cell and cell-matrix interactions, is a very promising one and has been shown to represent a very helpful adjunct to FNA biopsy of thyroid nodules." (PMID 26604924, 2015).
cardiac hypertrophy (27 papers, 2014 to 2025). "Both LGALS3 and miR-27b have a potential as therapeutic and diagnostic targets in the treatment of cardiovascular diseases, including myocardial hypertrophy." (PMID 35053194, 2021). "Besides, the loss of galectin-3 may delay the hypertrophic response after pressure overload on the heart, confirming the role of galectin-3 in mediating cardiac hypertrophy." (PMID 35191812, 2022). "Markers for pathologic cardiac hypertrophy (Anp), fibrosis (Col1a1, Col3a1, and Galectin-3), and inflammation (Cox2 and Tnf-α) were also assessed." (PMID 36986490, 2023). "In summary, the results of the present study indicated that Tan IIA attenuates cardiac hypertrophy by targeting galectin-3, suggesting that galectin-3 plays a critical role in cardiac hypertrophy and represents a new therapeutic target." (PMID 35191812, 2022). "In our previous study, we confirmed that galectin-3 mediated the inhibitory effect of miR-27b on cardiac hypertrophy." (PMID 35191812, 2022). "In the present study, we reported that Tan IIA inhibited the mRNA and protein expression of galectin-3 to exert its effect on cardiac hypertrophy." (PMID 35191812, 2022). "Increasing studies have reported that galectin-3 is involved in the progression of cardiac hypertrophy." (PMID 35191812, 2022). "In the study, it has been demonstrated that both up-regulation of miR-1 and miR-21 as well as galectin-3 lead to myocardial hypertrophy and unfavourable heart remodelling." (PMID 35053194, 2021). "Galectin-3 is known as an important mediator, which has a significant pathologic effect on cardiac hypertrophy and HF." (PMID 34722704, 2021). "Previous data have demonstrated a close link between Galectin-3 and accelerated cardiac hypertrophy in the pressure-overloaded myocardium, resulting in adverse myocardial remodelling and dysfunction." (PMID 34067808, 2021). "Numerous reports have indicated the participation of galectin-3 in myocardial fibrosis, myocarditis, hypertrophy of the heart muscle and ventricular dysfunction." (PMID 32119722, 2020). "Galectin-3(Gal-3), a β-galactosidase-binding lectin, is highly increased undervarious pathological conditions and promotes cardiac remodeling throughunderlying mechanisms regulating myocardial hypertrophy, inflammation, andfibrosis." (PMID 39077479, 2023). "Rescue experiments were performed to elucidate the role of galectin-3 in cardiac hypertrophy." (PMID 35191812, 2022). "We revealed, for the first time, that Tan IIA could prevent cardiac hypertrophy, mediated by m6A modification and the regulation of galectin-3 expression." (PMID 35191812, 2022). "Prior studies have identified galectin-3 as the most robustly up-regulated protein in models of cardiac hypertrophy and left ventricular dysfunction, and mice with a galectin-3 gene deletion develop myocardial hypertrophy without cardiac dysfunction and fibrosis." (PMID 27301475, 2016). "Additionally, when compared with vehicle, hrAnxA1 significantly decreased collagen deposition and the number of galectin-3–positive cells in K/BxN F1 hearts indicative of a negative impact on disease evolution to more advanced cardiac remodeling, including cardiac hypertrophy and fibrosis." (PMID 34526398, 2021). "Tan IIA suppressed m6A modification of galectin-3 via downregulating ALKBH5, which suppressed the development of cardiac hypertrophy." (PMID 35191812, 2022). "We revealed the role of Tan IIA in galectin-3 and m6A modification as well as the role of ALKBH5 in cardiac hypertrophy." (PMID 35191812, 2022).
cardiomyopathy (26 papers, 2011 to 2026). A disease of the heart muscle or myocardium proper. "Other studies focusing on a Han population found an association between a prognosis of heterogeneous cardiomyopathy with SNPs associated with LGALS3, AGCT, SLC25A13, HRG, APOB, SOD3, SYNM, and TLN2." (PMID 34572079, 2021). "This makes galectin-3 (Gal-3) a promising candidate for diagnosing the potential early onset of cardiomyopathy in T2DM patients." (PMID 39140033, 2024). "When subdividing patients into different types of cardiomyopathy, significantly higher Galectin-3 concentrations were detected in dogs with concentric cardiomyopathy compared to those with eccentric cardiomyopathy, such as DMVD." (PMID 35780161, 2022). "Besides, galectin-3 and copeptin are considered candidate biomarkers for the detection of early cardiomyopathy." (PMID 35069790, 2022). "Galectin-3 may be a promising biomarker in that setting for the diagnosis of AF-induced cardiomyopathy." (PMID 30067817, 2018). "Additionally, in patients with chronic Chagas cardiomyopathy, galectin-3 levels were correlated with cardiovascular biomarkers and diastolic dysfunction parameters, suggesting its potential as a prognostic marker in this specific cardiomyopathy." (PMID 39063659, 2024). "However, whether galectin-3 plays a major causative role in discussed process is not completely justified because there are studies showing that up-regulation of cardiac galectin-3 is not a critical disease modulator of cardiomyopathy induced by β2-adrenoceptor over-expression." (PMID 35053194, 2021).